KLK6 (kallikrein related peptidase 6)
Description:
Serine protease which exhibits a preference for Arg over Lys in the substrate P1 position and for Ser or Pro in the P2 position. Shows activity against amyloid precursor protein, myelin basic protein, gelatin, casein and extracellular matrix proteins such as fibronectin, laminin, vitronectin and collagen. Degrades alpha-synuclein and prevents its polymerization, indicating that it may be involved in the pathogenesis of Parkinson disease and other synucleinopathies. May be involved in regulation of axon outgrowth following spinal cord injury. Tumor cells treated with a neutralizing KLK6 antibody migrate less than control cells, suggesting a role in invasion and metastasis.
Synonyms: PRSS18; PRSS9; Bssp; Klk7; neurosin; SP59; hK6
Tractability: Small molecule: a structure with a bound ligand is known; a high-quality ligand is known. Antibody: its Gene Ontology location is reachable by antibodies, with high confidence; UniProt places it where antibodies can reach, with medium confidence; UniProt predicts a signal peptide or a membrane-spanning region. PROTAC: a small molecule that binds it is known.
Target class: Serine protease; Enzyme; Serine protease PA clan; Serine protease S1A subfamily; Protease
Gene: Protein-coding gene on chromosome 19 (50,958,631 to 50,969,673, reverse strand). Ensembl gene ENSG00000167755.
Subcellular location: Secreted; Nucleus, nucleolus; Cytoplasm; Mitochondrion; Microsome
Subcellular location (Human Protein Atlas): Nucleoplasm; Cytokinetic bridge; Nuclear membrane; Predicted to be secreted
Gene Ontology:
Molecular function: protein binding; serine-type endopeptidase activity; peptidase activity
Biological process: positive regulation of G protein-coupled receptor signaling pathway; amyloid precursor protein metabolic process; central nervous system development; collagen catabolic process; hormone metabolic process; myelination; protein autoprocessing; protein maturation; regulation of cell differentiation; response to wounding; tissue regeneration; proteolysis; regulation of neuron projection development
Cellular component: cytoplasm; extracellular region; nucleoplasm; secretory granule; cornified envelope; mitochondrion; nucleolus
Genetic constraint (gnomAD): Loss-of-function variants: 16 observed, 23.7 expected, observed/expected ratio (o/e) 0.68, 90% interval 0.46 to 1.02. The upper end of that interval is the gene's LOEUF score, 1.02, which puts it in group 4 of 6, group 1 being the genes least tolerant of losing a copy. Missense variants: 276 observed, 322.05 expected, observed/expected ratio (o/e) 0.86, 90% interval 0.78 to 0.95. Synonymous variants: 116 observed, 126.81 expected, observed/expected ratio (o/e) 0.91, 90% interval 0.79 to 1.07.
Homologues: Orthologues: chimpanzee KLK6 (99% identical), macaque KLK6 (98% identical), pig KLK6 (84% identical), dog KLK6 (78% identical), mouse Klk6 (68% identical), rat Klk6 (67% identical). Paralogues in human: KLK13 (51% identical), GZMB (36% identical), CMA1 (34% identical), GZMH (34% identical), CTSG (33% identical), AZU1 (29% identical).
Diseases named in the same sentence as KLK6 in open-access papers:
KLK6 is named in the same sentence as 144 diseases in open-access papers, as found by Europe PMC text mining. Sharing a sentence is not in itself a finding about the gene and the disease. The quoted sentences say what the papers report.
ovarian carcinoma (46 papers, 2002 to 2025). A malignant neoplasm originating from the surface ovarian epithelium. "For example, elevated levels of KLK6 are associated with higher grade, later stage and serous histotype ovarian cancer, all of which are associated with an unfavorable prognosis." (PMID 26231762, 2015). "Studies have suggested that high KLK6 expression was closely associated with shorter overall and recurrence-free survival for ovarian cancer and colon cancer patients." (PMID 23587030, 2013). "KLK6 was originally identified and cloned based on its aberrant expression in mammary and ovarian cancers and was proposed as a potential diagnostic biomarker." (PMID 23216878, 2012). "Recently, it was shown that stromal cell-associated expression of KLK6 is an indicator of poor prognosis in ovarian cancer patients." (PMID 23216878, 2012). "To further clarify KLK6's clinical utility and its role in ovarian cancer pathophysiology, we aimed to delineate the molecular processes underlying KLK6 overexpression in ovarian cancer." (PMID 17242704, 2007). "However, significant changes in the N-glycosylation patterns were observed for Asn61 of KLK3/PSA in prostate cancer, including an additional N-glycosylation site in the Asp95Asn variant, and for Asn132 of KLK6 in ovarian cancer." (PMID 41516101, 2025). "To delineate the processes underlying the overexpression of KLK6 in ovarian cancer, we first determined whether KLK6 was under transcriptional or translational upregulation." (PMID 17242704, 2007). "In particular, AAT appears to be the major inhibitor of KLK6 in body fluids, such as cerebrospinal fluid, serum, and ascites of ovarian cancer patients." (PMID 41516101, 2025). "KLK6 has thus become an emerging target in the field of ovarian cancer therapeutics, since it is present at the early stages of ovarian cancer progression." (PMID 37609678, 2023). "Emerging evidence correlates in vitro and in vivo cancer invasion and metastasis with increased activity of the proteases mesotrypsin (prostate and breast cancer) and kallikrein 6 (KLK6; ovarian cancer)." (PMID 37609678, 2023). "It has been suggested that KLK6 is responsible for increased E‐cadherin shedding, which increases metastasis and ascites in epithelial ovarian cancer." (PMID 37609678, 2023). "In this context, KLK6 is significantly upregulated in ovarian cancer (in addition to other types of cancer)." (PMID 37609678, 2023). "Peritoneal metastasis is more frequent and abundant in ovarian cancer where the expression of certain members (KLK6 and KLK10) of the KLK family in ascitic fluids from ovarian cancers has been reported." (PMID 35883559, 2022). "KLK-3 is a screening biomarker and an indicator of disease progression, and it has been studied extensively, while the other enzyme from this family, KLK-6, has been analyzed as a biomarker for ovarian cancer." (PMID 33996745, 2021). "Of note, there was a trend that KLK6 inhibition reduced the metabolic activity of the control tumour spheroids using KLK6-expressing ovarian cancer cells." (PMID 34439122, 2021). "In ovarian cancer, high KLK6 levels were detected in the stromal cells in poorly differentiated tumours (nuclear grade G3 versus G1/2)." (PMID 34439122, 2021). "Similar to KLK5, KLK6 is a biomarker for ovarian cancer, but is also overexpressed in colorectal cancers." (PMID 33150763, 2020). "Human KLK6 was originally identified by differential display for its potential implication in breast and ovarian cancer and named protease M." (PMID 27845893, 2017). "In immunohistochemical studies, we have previously observed that KLK5 as well as KLK6 protein expression by stromal cells within the tumor tissue of ovarian cancer patients significantly contribute to tumorigenicity." (PMID 29095848, 2017). "Analyses of our Proseek® data support these findings of a high correlation between KLK6 serum levels and late stage ovarian cancer." (PMID 29051715, 2017).
ovarian carcinoma (continued). "We found the specificity of KLK6 to be relatively high (88%) when comparing late stage ovarian cancer to healthy or benign cases; however the sensitivity was much lower (~ 40%) when comparing early stage ovarian cancer to healthy or benign cases." (PMID 29051715, 2017). "Intriguingly, glycosylation patterns of KLK3 and KLK6 seem to correlate with prostate and ovarian cancer stages." (PMID 27898009, 2016). "For example, changes in glycosylation patterns have been observed for KLK3 in prostate cancer and for KLK6 ovarian cancer." (PMID 26582203, 2016). "Ongoing research continues to investigate new promising biomarkers for the early detection of ovarian cancer, such as KLK6/7, GSTT1, PRSS8, FOLR1, and ALDH1." (PMID 26779384, 2015). "Several reports have shown that KLK6 is a promising biomarker of early diagnosis and unfavorable prognosis in several cancers, including ovarian cancer, colorectal cancer, gastric cancer, uterine cancer, lung cancer, and pancreatic cancer." (PMID 24669031, 2014). "KLK6 is an emerging new biochemical marker for clinical diagnosis of various forms of cancer, including ovarian cancer and for neurodegerative disorders." (PMID 23216878, 2012). "Promising biomarkers for early detection of ovarian cancer include KLK6/7, GSTT1, PRSS8, FOLR1, ALDH1, and miRNAs." (PMID 23319948, 2012). "In conclusion, we confirmed that KLK6 is significantly upregulated in ovarian cancer and serves as an unfavourable prognostic biomarker." (PMID 17242704, 2007). "In this study, we measured KLK6 expression in a large series of ovarian tissue cytosols and examined possible mechanisms of KLK6 up-regulation in ovarian cancer." (PMID 17242704, 2007). "Using a newly developed enzyme-linked immunosorbent assay (ELISA) with two monoclonal antibodies, we quantified KLK6 expression in ovarian tissue cytosols, and confirmed the upregulation of KLK6 in ovarian cancer and its unfavourable prognostic value." (PMID 17242704, 2007). "Lastly, we examined the role of alternative transcripts, genetic aberrations, and steroid hormones in the upregulation of KLK6 in ovarian cancer." (PMID 17242704, 2007). "Ample evidence supports the overexpression/increase of human KLK6 in both ovarian tumours and presurgical serum of patients with ovarian cancer." (PMID 17242704, 2007). "In this study, we found that steroid hormones play a minor role in the regulation of KLK6 in ovarian cancer." (PMID 17242704, 2007). "A weak positive correlation between tissue CA125 and KLK6 expression in ovarian cancer (Spearman correlation rs=0.566; P<0.001) was also observed." (PMID 17242704, 2007). "None of the steroid hormones produced any significant changes in KLK6 expression for the ovarian cancer cell lines." (PMID 17242704, 2007). "As potential therapeutics for advanced metastatic prostate, breast, and ovarian cancers, we report novel mesotrypsin‐ and KLK6‐based therapies, based on our previously developed mutants of the human amyloid β‐protein precursor Kunitz protease inhibitor domain (APPI)." (PMID 37609678, 2023). "In addition, the elevation of KLK6 expression has been reported in the kinds of literature, such as melanoma, ovarian cancer, gastric cancer, pancreatic ductal adenocarcinoma, and colon cancer." (PMID 36193495, 2022). "Kallikrein 6 (KLK6) levels have been shown to be elevated in patients with multiple types of malignancies, including glioblastoma, colorectal, laryngeal, gastric, and ovarian cancers, as well as prostate cancer." (PMID 33490732, 2021). "This is similar to the KLK6 staining pattern observed in ovarian cancer tissues." (PMID 34439122, 2021). "KLK6 is down-regulated in breast cancer cell lines characterized by a high degree of malignancy but is strongly expressed at the mRNA level in primary cultures of breast cancer cells and ovarian cancer tissue and ovarian cancer cell lines." (PMID 32655372, 2020).
ovarian carcinoma (continued). "Human KLK6 (initially named protease M/zyme/neurosin), is a member of the kallikrein-related peptidase family of proteins, originally identified and cloned based on its aberrant expression in human breast and ovarian cancer." (PMID 31692974, 2019). "Importantly, CA125 and HE4 are present in this quadrant, as well as other proteins that have been reported to be elevated in the sera of women with ovarian cancer, such as interleukin-6, midkine, folate receptor-alpha, KLK6, and hK11." (PMID 29051715, 2017). "Many of the same proteins that were identified by unsupervised hierarchical clustering and by linear regression analysis, were also significantly higher in the late stage ovarian cancer patients relative to the healthy women, e.g. MK, KLK6, hk11, CXCL13, FR-alpha, IL-6, and FADD." (PMID 29051715, 2017). "In addition, KLK6 has been identified as a marker of poor prognosis in colon and ovarian cancer patients." (PMID 25635769, 2015). "By contrast, as a result of its upregulation in human colon cancer, gastric cancer, ovarian cancer and melanoma, KLK6 has been identified as a potential target for pharmacologic intervention, as well as a prognostic indicator for disease progression and survival." (PMID 25635769, 2015). "KLK6-positive ovarian cancer patients show an increased risk of relapse and death compared to KLK6 negative, and the combination of KLK6 and CA-125 enhances the diagnostic power." (PMID 23216878, 2012). "KLK6, KLK10, and KLK11 may provide novel serological diagnostic markers since their expression levels in serum are significantly higher in ovarian cancer patients than in healthy subjects." (PMID 23319948, 2012). "Lastly, we evaluated the role of steroid hormones in the regulation of KLK6 in ovarian cancer." (PMID 17242704, 2007). "In this study, we first quantified KLK6 expression, using a newly developed immunoassay with two monoclonal antibodies, in a relatively large series of ovarian cancer tissue specimens, and confirmed the prognostic value of KLK6 for ovarian cancer." (PMID 17242704, 2007). "Our results confirmed the value of KLK6 as an unfavorable prognostic biomarker for ovarian cancer." (PMID 17242704, 2007). "Therefore, differential expression of alternative transcripts cannot account for KLK6 upregulation in ovarian cancer." (PMID 17242704, 2007). "Twelve kallikreins, including KLK6, are concurrently upregulated in ovarian cancer." (PMID 17242704, 2007). "Potential gene amplification of KLK6 in ovarian cancer has also been suggested." (PMID 17242704, 2007). "Elevated KLK6 levels have been associated with late stage ovarian cancer but not benign tumors." (PMID 29051715, 2017). "Hence, the up-regulation of KLK6 seems to be specific to ovarian cancer." (PMID 17242704, 2007). "Hence, we sequenced all KLK6 exons and the 5′-flanking region for ovarian tumours with various KLK6 levels to determine if genetic aberrations may account for the upregulation of KLK6 in ovarian cancer." (PMID 17242704, 2007). "Therefore, KLK6 could be used in conjunction with other kallikreins, as well as non-kallikrein biomarkers in future multiparametric prognostic tests for ovarian cancer." (PMID 17242704, 2007). "Here, we report, for the first time, mesotrypsin‐ and KLK6‐targeted therapies derived from human APPI for advanced metastatic prostate, breast, and ovarian cancers." (PMID 37609678, 2023). "We focus on mesotrypsin and kallikrein 6 (KLK6) as protease targets and on prostate, breast, and ovarian cancer as proof‐of‐concept." (PMID 37609678, 2023). "Activation of the TGFβ pathway was also observed in a proteomic analysis of the secretome of an ovarian cancer cell line engineered to overexpress KLK4, KLK5, KLK6 and KLK7." (PMID 33255452, 2020). "Elevated levels of Kallikrein 6 and 7 (KLK6 and KLK7) was reported in sera of ovarian carcinoma subtypes, depicting their potential to improve early detection of OC." (PMID 31608277, 2019).
ovarian carcinoma (continued). "Pointing to potential cancer-type specific effects as described for KLK6, KLK8 is a favorable prognostic indicator in ovarian cancer, but an unfavorable indicator in lung cancer." (PMID 26231762, 2015). "Overexpression of KLK6 and KLK7 mRNA was specific to ovarian cancer, in particular to serous and papillary serous subtypes." (PMID 25477184, 2014). "Two kallikrein (KLK) serine protease family members (KLK6 and KLK7) were found to be significantly overexpressed relative to normal controls in most of the ovarian cancer cell lines examined." (PMID 25477184, 2014). "We have reported that combined expression of KLK4, KLK5, KLK6, and KLK7 in OV-MZ-6 ovarian cancer cells regulates integrin expression, cell adhesion, and promotes a malignant phenotype." (PMID 27605189, 2013). "Our results showed that KLK6 and KLK7 are upregulated in ovarian cancer tissues over other cancer types." (PMID 23319948, 2012). "Prostasin (PRSS8), GSTT1, FOLR1, KLK6, KLK7, and ALDH1 are all currently under research and clinical trials and are also potential biomarkers for early detection of ovarian cancer." (PMID 23319948, 2012). "We examined the effects of steroid hormones on KLK6 expression in BG-1, CaOV3 and OVCAR-3 epithelial ovarian cancer cell lines, as well as the hOSE cell line." (PMID 17242704, 2007). "Hence, KLK6 may also serve as a therapeutic target for ovarian cancer." (PMID 17242704, 2007). "Using this approach, we have previously reported that several candidates including hepsin, stratum corneum chymotryptic enzyme (SCCE/KLK7), protease M (KLK6), TADG-12, and TADG-14 (KLK8) are abundantly expressed in ovarian cancers." (PMID 15611789, 2005). "KLK6 and KLK10 in particular are highly expressed in ovarian cancer." (PMID 40836974, 2024). "In addition to the well-known ovarian cancer serum biomarkers CA125 and HE4, we identified six additional proteins, MK, hK11, KLK6, FRα, PRSS8, and IL-6, that had previously been reported as serum biomarkers for ovarian cancer." (PMID 29051715, 2017). "We have previously demonstrated that KLK6 and KLK7 can serve as ovarian cancer-specific biomarkers." (PMID 27036110, 2016). "KLK4, KLK5, KLK6 and KLK7 have been found related to the prognosis of ovarian cancer." (PMID 27825132, 2016). "Assays based on KLK6 and KLK7 expression may provide specific and sensitive information for early detection of ovarian cancer." (PMID 25477184, 2014). "Elevated expression of KLK4, KLK5, KLK6, and KLK7 are linked to multi-cellular aggregation of ovarian cancer cells and non-responsiveness of patients to paclitaxel." (PMID 27605189, 2013). "Among these, KLK6, KLK7, KLK8, and KLK10 showed the highest statistical significance in ovarian cancer effusions over other cancer groups, suggesting that these kallikreins might be useful biomarkers in differential diagnosis of ovarian cancer." (PMID 23319948, 2012). "However, the sensitivity and specificity of both KLK6 and CA125 are ineffective in screening a population for early detection of ovarian cancer." (PMID 23319948, 2012). "KLK6 has been identified as having high potential as a novel biomarker with better specificity than CA125 for early detection of ovarian cancer because it is not elevated in noncancerous tumors." (PMID 23319948, 2012). "The increased aggressiveness of the KLK6 clone was not unexpected as KLK6 overexpression is thought to be an early phenomenon in ovarian carcinoma development." (PMID 22102857, 2011). "Nevertheless, the overexpression of KLK6 in ovarian cancer is probably not due to differential expression of alternative transcripts, mutations in the exons and proximal 5′-flanking region, or steroid hormone regulation." (PMID 17242704, 2007). "The KLK6 locus in ovarian cancer patients has not previously been scrutinised for genetic aberrations." (PMID 17242704, 2007).